TLR4 (toll like receptor 4)
Diseases named in the same sentence as TLR4 in open-access papers (continued):
Sharing a sentence is not in itself a finding about the gene and the disease.
polycystic ovary syndrome (15 papers, 2020 to 2026). A disorder that manifests as multiple cysts on the ovaries. "A previous report revealed that GCs from women with polycystic ovary syndrome (PCOS) express higher levels of TLR4, which is associated with lower embryo quality." (PMID 33776924, 2021). "For instance, SGD suppresses the inflammation in polycystic ovary syndrome by inhibiting Toll-like receptor 4/nuclear factor kappa B (TLR4/NF-κB) Pathway." (PMID 39296087, 2024). "Toll-like receptor 4 mediates the activation of the IRF7/NF-κB pathway to aggravate inflammation in polycystic ovary syndrome." (PMID 36336986, 2023). "Chang and colleagues reported that this compound markedly inhibited the production of inflammatory mediators in rats with polycystic ovary syndrome by blocking TLR4/NF-κB signal pathway." (PMID 37109641, 2023). "We analyzed leukocyte cell surface and gene expression of toll-like receptors 2 and 4 (TLR2 and TLR4) during fasting and after macronutrient loads in women with polycystic ovary syndrome and female and male controls." (PMID 31936430, 2020). "CRY may prevent ovarian tissue damage caused by polycystic ovary syndrome through the regulating the expression and function of HMGB1, TLR4, and NF-κB." (PMID 41301950, 2025). "In addition, this herb has been shown to inhibit the secretion of inflammatory mediators in rats with polycystic ovary syndrome by blocking the TLR4/NF-κB signaling pathway." (PMID 40283919, 2025). "On the other hand, the expression of TLR4 and TNFα was only affected by hyperandrogenemia." (PMID 39268230, 2024). "In polycystic ovary syndrome (PCOS) rat models, ST inhibited autophagy and inflammation by inhibiting the PI3K/AKT/mTOR and TLR4/NF-κB pathways, respectively." (PMID 38131990, 2023).
Shock (15 papers, 2012 to 2023). The state in which profound and widespread reduction of effective tissue perfusion leads first to reversible, and then if prolonged, to irreversible cellular injury. "TLR4 activation also leads to the release of histamine, causing vasodilation, and activates clotting factors that lead to problems such as thrombosis, acute disseminated intravascular coagulation, hemorrhage, and septic shock." (PMID 36982478, 2023). "This is in line with data showing the critical role of TLR4 and NF-κB activation in HIF-1α activation during trauma/hemorrhagic shock-induced acute lung injury after lymph infusion in wild-type mice, in comparison to mice that harbor a TLR4 mutation and/or NF-κB inhibitors." (PMID 35682644, 2022). "In the CRAB-induced septic shock mouse model, rhamnetin reduced the level of lipopolysaccharide (LPS) in lung lysates, resulting in the inhibition of TLR4-mediated inflammatory signaling." (PMID 37958587, 2023). "We further showed that knocking down YAP in the heart activated TLR4/NF-κB signaling and exacerbated LPS-induced cardiac shock." (PMID 34206257, 2021). "In the case of infection caused by gram-negative bacteria, the mediators for the innate immune system response, especially TLR4, are already significantly enhanced; thus, an anti-endotoxin agent should be able to block the LPS-induced septic shock." (PMID 33263333, 2021). "In our data, Tlr4 was suppressed in WT and cGAS−/− neutrophils when activated with LPS, which is in line with another report on alveolar macrophages from a rodent model of lung injury after resuscitation from hemorrhagic shock." (PMID 37189826, 2023). "This supports the hypothesis that stress in the form of hemorrhagic shock blurs some of the baseline differences between WT and TLR4-/- mice." (PMID 35663944, 2022). "In addition, the pathogenesis of LPS-induced septic shock has been well described in the literature, with the involvement of the toll-like receptor 4 (TLR4)-dependent inflammatory cascade, resulting in an excessive secretion of TNF-α and interleukins." (PMID 35628471, 2022). "Notably, after 2h of hemorrhagic shock, overall tissue distribution of inflammatory mediators was fairly similar in WT and TLR4-/- mice." (PMID 35663944, 2022). "The main event which occurs upon binding of LPS to TLR-4 is nuclear localization of the transcription factor NF-κB, which upon binding to its promoter, results in transcription of inflammatory cytokines; an event at the heart of septic shock." (PMID 22363498, 2012). "This study provides evidence that transduced PEP-1-HO-1 fusion protein may reduce the septic shock-induced increase of TLR4 expression and NF-κB activation and alleviate septic shock-induced lung injury through the antioxidant, anti-inflammatory, and antiapoptotic properties of transduced HO-1." (PMID 29682161, 2018). "We documented the early time course evolution of circulatory Prdx1, hypoxic marker carbonic anhydrase IX, inflammatory cytokines including IL-6, IL-8, IL-10, MCP-1, TNF-α, IL-1β, and danger signaling receptors (TLR4 and CD14) in a cohort of cardiogenic shock patients within 1 day after ECMO support." (PMID 27142532, 2016). "Finally, in vivo work demonstrated that HMGB1 contributes to the development of lung injury after severe hemorrhage and that HMGB1-mediated lung inflammation depends on TLR4 in the early phase and on TLR2 in the late phase following hemorrhagic shock." (PMID 23696858, 2013).
adenoma (14 papers, 2010 to 2025). A neoplasm arising from the epithelium. "Moreover, in KO mice, the values of TLR-4 in the stromal compartment (again associated with cells of macrophage morphology) of the adenocarcinomas were elevated and statistically different form the values of adenoma specimens (p < 0.05)." (PMID 21059221, 2010). "TLR4 expression was significantly higher in CRC compared to adenoma cases (66.5% vs 30.5%, p<0.001)." (PMID 40703545, 2025). "First, we demonstrated distinct expression patterns between CRC and adenomas, with significantly higher TLR4 expression and predominant high-level MyD88 expression in CRC tissues." (PMID 40703545, 2025). "Combined TLR4/MyD88 expression analysis revealed significantly elevated scores (≥5) in CRC compared to adenoma cases (34.1% vs 12.2%, p<0.001)." (PMID 40703545, 2025). "First, coordinated TLR4/MyD88 expression during adenoma-carcinoma progression remains poorly characterized." (PMID 40703545, 2025). "First, we demonstrated distinct expression patterns of TLR4/MyD88 between CRC and adenomas, characterized by significantly higher TLR4 expression in CRC tissues and predominant high-level MyD88 expression in CRC cases." (PMID 40703545, 2025). "While TLR4 expression was elevated in CRC compared to adenomas, the majority (61.4%) of TLR4-positive cases showed low expression intensity, particularly in advanced stages." (PMID 40703545, 2025). "Based on the pathology scores, CLDN1 and TLR4 were the only two marker proteins that effectively distinguished adenomas and adenocarcinomas from normal colon samples by this scoring method." (PMID 26894861, 2016). "At least one of the two protein markers, claudin 1 or toll-like receptor 4, scored ≥4 in 83% of adenoma and adenocarcinoma samples in the CRC TMA." (PMID 26894861, 2016). "Mean TLR4 epithelial staining scores were lower in adenomatous polyps than normal tissue controls (adenoma 0.57 versus normal 0.67, W = 67, p = 0.30)." (PMID 24887394, 2014). "Using cytokeratin staining to identify epithelium, we found that TLR4 is over-expressed in a subset of tumors and that the expression increases from normal to adenoma to cancer." (PMID 24887394, 2014). "This series found that malignant neoplastic tissue had lower TLR4 expression than adenomas from patients with CRCs (adenoma vs malignancy: 0.54 vs 0.06, coef = −0.43, p = 0.021) (GSE12225)." (PMID 24887394, 2014). "TMAs consisting of 182 independent cancers, 19 adenomas, and matched normal tissue were examined for TLR4 expression." (PMID 24887394, 2014). "Increasing TLR4 expression was seen with advancing tumor stage and was also over-expressed in some adenomas." (PMID 24887394, 2014). "Mean TLR4 stromal staining scores were lower in adenomatous polyps (n = 14) than normal tissue (n = 12) controls (adenoma 2.29 versus normal 3.5, W = 95, p = 0.58)." (PMID 24887394, 2014). "A recent comparative immunohistochemistry analysis between normal mucosa and adenomas showed that TLR4 and MD2 are overexpressed in 20 and 23% of the adenomas, respectively, further substantiating the involvement of the TLR4 pathway in CRC." (PMID 25076949, 2014). "Our transcriptome data demonstrated high TLR4 expression in adenomas relative to normal tissue and, to a lesser degree, higher expression relative to cancer." (PMID 24887394, 2014). "To address this question, we examined tissue arrays composed of adenomas and sporadic CRCs for TLR4 expression by immunofluorescent staining." (PMID 23691015, 2013). "Given that TLR4 expression is increased in the epithelial compartment of adenomas and cancer, we chose to model this observation in mice." (PMID 23691015, 2013). "In this study, we performed a systematic immunohistochemical analysis of TLR4 and MyD88 expression in normal colon mucosae, adenomas, and CRC." (PMID 20145615, 2010). "Compared with normal mucosae and adenomas, the expression of TLR4 was detected in a high proportion of cancers (78 of 108, 72%)." (PMID 20145615, 2010).
adenoma (continued). "Compared with normal mucosae and adenomas, 20% cancers displayed high expression of TLR4, and 23% cancers showed high expression of MyD88." (PMID 20145615, 2010). "In adenomas, TLR4 expression was exclusively of low intensity when present." (PMID 40703545, 2025). "Interestingly, CD14 a co-receptor of TLR4 is downregulated in our study, contrary to TLR4 expression in adenoma." (PMID 35486660, 2022). "Similarly for TLR4, 63% and 45% of adenomas and adenocarcinomas scored ≥4, with only 7% of normal samples scoring ≥4." (PMID 26894861, 2016). "So we could suggest more expression and/or activation of TLR-4/MyD88 in adenomas and adenocarcinomas." (PMID 26504896, 2015). "TLR4 may play distinct roles in the transition from normal colon to adenoma and from a local to a more advanced tumor." (PMID 24887394, 2014). "We speculate that adenomas may represent a more homogeneous tissue than cancer or that TLR4 plays an important role in tumor promotion from adenoma to cancer." (PMID 24887394, 2014). "Our results demonstrate that TLR4 is expressed in adenomas and CRCs." (PMID 24887394, 2014). "All four probes for TLR4 were significantly different between normal tissue and adenomas or cancer." (PMID 24887394, 2014). "Given that certain adenomas and CRCs over-express TLR4, we asked whether TLR4 functioned as a tumor promoter." (PMID 23691015, 2013). "We asked whether TLR4 expression characterized a subset of adenomas and CRCs." (PMID 23691015, 2013). "Immunohistochemical expression analysis of TLR4 and MyD88: comparison between CRC and adenoma cases." (PMID 40703545, 2025). "IHC staining of unmatched normal colon, adenoma, and CRC patient samples for TLR4, vimentin, and CD68 was performed in a limited cohort to identify myofibroblasts and macrophages, respectively." (PMID 24887394, 2014). "In this study, we observed that TLR4/MyD88 signalling was frequently overexpressed in CRC compared with normal mucosae and adenomas." (PMID 20145615, 2010). "TLR4 expression was significantly higher in CRC compared to adenomas (66.5% vs 30.5%, p<0.001), with MyD88 showing widespread expression in both groups (CRC: 97.2%, adenoma: 95.4%)." (PMID 40703545, 2025). "The most striking finding was the significantly higher TLR4 expression in CRC tissues (66.5% vs 30.5%, p<0.001), while MyD88 showed widespread expression in both groups with comparable overall positivity rates (CRC: 97.2%, adenoma: 95.4%)." (PMID 40703545, 2025). "Similar to that of TLR4, MyD88 expression was absent or very weak in normal mucosae, cancer margin samples, and adenomas." (PMID 20145615, 2010). "The expression of TLR4 and MyD88 in 108 CRC samples, 15 adenomas, and 15 normal mucosae was evaluated by immunohistochemistry, and the correlations between their immunoscores and clinicopathological variables, including disease-free survival (DFS) and overall survival (OS), were analysed." (PMID 20145615, 2010). "TLR4 expression was higher in adenomas than cancers; length of TLR4 transcript had no influence." (PMID 24887394, 2014). "Using a TLR4 scoring system (negative = 0, low positive = 1, positive = 2, high positive = 3), we demonstrate that 22% of adenomas and 38% of sporadic CRCs show increased expression of TLR4 (score 2–3) compared to 8% of normal tissues (8% score 2–3, 92% score 0–1)." (PMID 23691015, 2013).
amyotrophic lateral sclerosis (14 papers, 2015 to 2026). Amyotrophic lateral sclerosis (ALS) is a neurodegenerative disease characterized by progressive muscular paralysis reflecting degeneration of motor neurons in the primary motor cortex, corticospinal tracts, brainstem and spinal cord. "Increased expression of TLR4 in microglial cells has been observed in animal models and patients of Alzheimer's disease (AD), Parkinson's disease (PD), and Amyotrophic Lateral Sclerosis (ALS)." (PMID 27293318, 2016). "Subsequently, increased expression of TLR4 is also found in PD, AD, and amyotrophic lateral sclerosis (ALS) patients as well as in animal models." (PMID 31815123, 2019).
anemia (14 papers, 2008 to 2025). A reduction in the number of red blood cells, the amount of hemoglobin, and/or the volume of packed red blood cells. "Here, we have found both TLR4 Asp299Gly and Thr399Ile polymorphisms to cause a 3.8 -5.3-fold increased risk of severe anaemia and 3.5 – 4.4-fold increased risk of high parasite density, while Thr399Ile polymorphism alone raised the risk of fever 5-fold." (PMID 27350800, 2015). "Model investigating whether severe anemia ± RBC transfusion contributes to development and severity of NEC, activating TLR4-signalling mechanisms to drive inflammation and injury; Can be used to evaluate risk factor of iatrogenic anemia and gut perfusion." (PMID 37082706, 2023). "The TLR4 SNP (299AG) was associated with severe anemia and hyperparasitemia in Ghanaian children." (PMID 34698295, 2021). "Results from current study showed that infant anemia was associated with decreased pro-inflammatory cytokine responses to TLR1-2 and TLR4 stimulation, as well an increased prevalence of nasopharyngeal colonization with M. catarrhalis." (PMID 29559671, 2018). "In summary, anemia in infancy was associated with reduced pro-inflammatory cytokine response to TLR1-2 and TLR4 stimulation, as well an increased prevalence of nasopharyngeal colonization with M. catarrhalis." (PMID 29559671, 2018). "Studies have described a murine model of NEC instigated by transfusions after anemia, illustrating typical NEC-like gut injuries in the anemia-transfusion group within 48 h post transfusion due to Toll-like receptor-4-mediated injury and intestinal epithelial barrier dysfunction." (PMID 38906930, 2024). "In this study, severe anemia was found to cause inflammatory changes in the intestinal mucosa with macrophage infiltration, and the subsequent RBC transfusions further activated these cells via a TLR4-mediated mechanism to cause injury." (PMID 37082706, 2023). "Severe anemia caused a low-grade inflammatory state in the intestinal mucosa with macrophage infiltration, and subsequent RBC transfusions activated these cells via a TLR4-mediated mechanism to cause bowel injury." (PMID 31375667, 2019). "Tlr4 could still participate in the regulation of anaemia and parasitaemia, which are not correlated with survival." (PMID 21085469, 2010).
Hydrocephalus (14 papers, 2018 to 2024). Hydrocephalus is an active distension of the ventricular system of the brain resulting from inadequate passage of CSF from its point of production within the cerebral ventricles to its point of absorption into the systemic circulation. "IVH-triggered TLR4 signaling stimulates CSF secretion >3.5-fold and causes hydrocephalus by increasing functional expression of pSPAK and pNKCC1 in CPe3." (PMID 31911626, 2020). "Microglia activation in hydrocephalus involved TLR-4 and RAGE as the receptor of Damage associated molecular patterns (DAMPS) and downstream signaling of the nuclear factor-κB (NF-κB) pathway." (PMID 32684804, 2020). "In a mouse model of posthemorrhagic hydrocephalus, Toll-like receptor 4–nuclear factor kB (NF-kB) signaling has been described as an important pathway in mediating hydrocephalus development by causing further damage to the ependymal cells or CSF hypersecretion from the choroid plexus epithelium." (PMID 31771992, 2019). "In this study, we aim to detect the role of Toll‐like receptor 4/nuclear factor‐kappa B/Na+/K+/2Cl‐cotransporter 1(TLR4/NF‐κB/NKCC1) signal pathway in the development of hydrocephalus." (PMID 39450988, 2024). "And attenuated abnormal CPE secretion and hydrocephalus by inhibiting TLR4 / NF-κB / NKCC1 and AQP1." (PMID 39839745, 2024). "All these suggested that TLR4 is also highly expressed in CPECs and involved in hydrocephalus formation after intracerebral hemorrhage." (PMID 36497041, 2022). "The Toll-like receptor 4 (TLR4) protein-dependent inflammatory response contributes to hydrocephalus by inducing hypersecretion of CSF." (PMID 35729645, 2022). "Systemic inflammation mediated via TLR4 increases choroid plexus CSF secretion, and likely contributes to ventriculomegaly in hydrocephalus." (PMID 30319361, 2018). "Interventions in the early stage of hydrocephalus (within 3 days) may reduce the abnormal secretion of cerebrospinal fluid and the occurrence of hydrocephalus by inhibiting the activation of TLR4/NF‐κB/NKCC1 pathway." (PMID 39450988, 2024). "explored the pathophysiological mechanisms of intraoperative hemorrhage leading to the progression of hydrocephalus and found that hemorrhage can stimulate choroid plexus epithelial cells to produce an inflammatory response through factors like Toll-like receptor 4 and nuclear factor-κB." (PMID 37916175, 2023). "Previous studies have identified quantitative proteomics signatures in post-hemorrhagic hydrocephalus and idiopathic normal pressure hydrocephalus, these finding suggests that TLR4-NF-κB, mTOR, PDGFRα signaling and other pathways play an important role in hydrocephalus." (PMID 36052359, 2022). "Additionally, the degree of hydrocephalus in the experimental group was found to be markedly reduced by injecting TLR4 antagonist into the rat model of intraventricular hemorrhage." (PMID 36497041, 2022). "Genetic deletion of TLR4 or SPAK was found to normalize CSF secretion, suggesting that inhibition of the TLR4-NFκB signaling pathway or the formation of the SPAK-NKCC1 complex could have a therapeutic effect on hydrocephalus." (PMID 35715859, 2022). "The TLR4-NF-κB pathway is a critical mediator of the innate immune response, and inhibition of TLR4 signaling attenuated ventriculomegaly as well as markers of ependymal inflammation in post hemorrhagic models of hydrocephalus." (PMID 35306341, 2022). "Therefore, it was speculated by us that the activated TLR4 in CPECs is also involved in the production of hydrocephalus after SAH." (PMID 36497041, 2022). "TLR4/NF‐κB/NKCC1 and AQP1 can prevent the prosses of hydrocephalus." (PMID 39450988, 2024). "Interestingly, both genetic knockout and intrathecal pharmacological knockout of either TLR4 or SPAK was found to attenuate the CSF hypersecretion and therefore treat the hydrocephalus, providing a strong preclinical mechanistic link, at least in mice." (PMID 36050779, 2022).